CXCL1 (C-X-C motif chemokine ligand 1)
Diseases named in the same sentence as CXCL1 in open-access papers (continued):
Sharing a sentence is not in itself a finding about the gene and the disease.
glioblastoma (continued). "However, CXCL1, which is formed by glioblastoma cells, leukocytes and astrocytes alike, and which could be important for tumor immunogenicity, may also have neuroprotective effects." (PMID 35965529, 2022). "In glioblastoma (GBM), the high expression of CXCL1 was related to poor prognosis of patients induced radiotherapy resistance through EMT event and using activation of NF-κB signaling." (PMID 34900673, 2021). "CXCL1 also induces the recruitment of endothelial progenitor cells (EPC) into the tumor niche, as shown in experiments on glioblastoma multiforme." (PMID 40427171, 2025). "In glioblastoma multiforme cells, there was a much greater increase in CXCL8/IL-8 expression compared to CXCL1." (PMID 40427171, 2025). "Elevated levels of CXCL1 or CXCL2 promote myeloid cell migration while disrupting the accumulation of CD8 T cells at the tumor site, leading to accelerated glioblastoma progression." (PMID 39660865, 2025). "The results indicated that the source of CCL5, CCL7, and CXCL1 in our experimental system was mainly MSCs, while CXCL16 was predominantly secreted by glioblastoma U251 cells." (PMID 39272976, 2024). "Our study shows the cells grown in 3D-GMH with serum overexpress and secrete CXCL1, CXCL5, IGFBP2, PTX3, THBS1, VEGFA, and VCAM1—all genes expressed in perivascular or perinecrotic zone of glioblastoma tissues that are hotspots for immune cells." (PMID 34489494, 2021). "We hypothesized the existence of a proliferative signaling loop involving CXC chemokines (e.g., CXCL1 and CXCL8) and their receptors (e.g., CXCR1 and CXCR2) in glioblastoma growth." (PMID 40362634, 2025). "While most of the analyzed chemokines (listed in Section 2) were not released by ferroptotic glioblastoma cells, we detected variations for CXCL1, CCL18, CCL20, and CCL22; however, these were not significant when comparing RSL3 to RSL3/liproxstatin-1." (PMID 41300529, 2025). "Glioblastoma CSC-derived exosomes can stimulate M2 polarization, programmed death-ligand 1 (PD-L1) expression, and the production of monocyte chemotactic protein 3 (MCP-3) and CXCL1, which promote myeloid cell recruitment, through the STAT3 pathway in glioblastoma." (PMID 36672697, 2023). "There, genes with a higher expression in glioblastoma compared to astrocytoma were VEGFA, 4EBP1, CCL2, PLAU (uPA), CXCL8 (IL8), CXCL10 (IP10), CASP8, HGF, LIF, CD40, CDCp1, TNFRSF11B (OPG), CD274 (PD-L1), IL6, CXCL1, CCL20 (MIP3α), CCL8 (MCP2), CD244, MMP1, TNFRSF9, CXCL6, MMP10, FGF5)." (PMID 35301393, 2022).
periodontitis (26 papers, 2017 to 2026). An acute or chronic inflammatory process that affects the tissues that surround and support the teeth. "Conversely, testosterone therapy in transgender males increases pro-inflammatory cytokines (e.g., TNF-α, IL-1α, CXCL1) and Th17 cells, potentially heightening inflammation in periodontal tissues and elevating periodontitis risk." (PMID 39917660, 2024). "Another study, assessing candidate genes associated with periodontitis, identified CXCL1 using an integrative gene ranking method as one of the genes requiring further experimental assessment for its potential role in periodontitis." (PMID 29731776, 2018). "The increased expression of CXCL1 in periodontitis may be caused by other factors such as high mobility group box 1 (HMGB1)." (PMID 35806156, 2022). "Enhancement of CXCL1 expression in gums has been reported to normalize diabetes - and insulin-resistant induced neutrophil recruitment and delayed periodontitis." (PMID 40176796, 2025). "Therapeutic modulation of CXCL1 dysregulation in fibroblasts represents a promising strategy not only for periodontitis management but also for ameliorating diabetes-related complications, including insulin resistance and impaired wound healing." (PMID 40176796, 2025). "The investigation revealed significantly elevated CXCL1 expression levels in gingival tissues obtained from both human subjects and rat models with periodontitis, when compared to healthy periodontal sites." (PMID 40176796, 2025). "According to previous evidence, CXCL1 does participate in the occurrence of periodontitis, which further validates the feasibility and scientificity of our algorithm." (PMID 40176796, 2025). "To confirm that these observations were not simply a result of excessive neutrophilrecruitment, we examined the expression of a neutrophilic cytokine CXCL1, which is highly expressed in gingival keratinocytes affected by periodontitis." (PMID 39650645, 2024). "Our results showed that gavage of periodontitis saliva increased the expression of inflammatory factors, including Il-1β, Tnf-α, Cxcl1, Cxcl2, and Ccl2, in the ischemic brain in mice." (PMID 35663549, 2022). "In the present study, we also observed that the levels of IL-8 and CXCL1, two neutrophil chemoattractant chemokines, were significantly higher in the saliva from the periodontitis subjects than in the saliva from the healthy subjects." (PMID 35048079, 2021). "The mean salivary concentrations of CXCL1 and IL-8 were 2.3 times higher (p = 0.03) and 3.1 times higher (p = 0.02), respectively, in the periodontitis subjects than in the healthy subjects." (PMID 35048079, 2021). "There was also a significant difference in the level of CXCL1 in gingival crevicular fluid between healthy and periodontitis subjects." (PMID 33322059, 2020). "Higher levels of CXCL1 were found in human and rat gingiva from periodontitis sites compared with periodontally healthy sites." (PMID 33322059, 2020). "Among these promising genes, involved, or potentially involved, in periodontitis CXCL1 and MMP3 were also identified in our present study as being gene induced in young GFs in response to F. nucleatum infection." (PMID 29190775, 2017). "Previous studies have reported heterogeneity in gingival fibroblasts in periodontal tissues, with four subsets significantly altered in periodontitis: Fib 1.1 (CXCL1, CXCL2, CXCL13); Fib 1.2 (APCDD1, IGFBP2, MRPS6); Fib 1.3 (APOD, GSN, CFD); and Fib 1.4 (TIMP3, ASPN, COL11A1)." (PMID 40801798, 2025). "Similarly, keratinocytes in periodontitis patients show increased expression of CXCL1, CXCL3, CXCL8, CXCL13, and CCL20, suggesting that chemokine expression in gingival fibroblasts and epithelial cells drives chronic periodontitis." (PMID 40565042, 2025). "In another work integrating the single-cell transcriptome, it was found that CXCL1 inhibited by curcumin could exert therapeutic potential in the management of periodontitis." (PMID 40176796, 2025).
periodontitis (continued). "We can speculate that the increases in TNF-α, IL-1α, CXCL1, CCL2, and Th17 responses following testosterone GAHT therapy could increase inflammation in periodontal tissues, potentially elevating periodontitis risk." (PMID 39917660, 2024). "In humans with periodontitis, there is an increased amount of CXCL1 in the affected gingiva." (PMID 35806156, 2022). "We detected a significant increase in mRNA levels of Interleukin (IL)-1β, IL-17 and the chemokines Cxcl1 and Cxcl2 which are important neutrophil chemoattractants (corresponding to Cxcl8 in humans) in gingival tissue derived from CD73-deficient animals with periodontitis when compared to the WT." (PMID 38152410, 2023). "Of these, CXCL1 and CXCL8 were significantly upregulated after P. gingivalis infection and also upregulated in periodontitis epithelial cells from scRNA-seq data." (PMID 41358003, 2025). "In the process of periodontitis, chemokines such as CXCL-8, CXCL-1, and CCL-5 and cytokines such as TNF-α, IL-1β, and IL-6 are present, due to the action of these multi-factors, it progresses to severe periodontitis with loss of periodontal support structures." (PMID 40733170, 2025). "Focusing on how this impacted keratinocytes, we found chemokine signatures such as CXCL1/3/8/17 and CCL20 that had been found in previous analyses, in both periodontitis and health." (PMID 38876998, 2024). "Salicin treatment significantly inhibited the expression of CXCL1, CXCL2 and CXCL5 in the gingival tissue of WT-periodontitis mice, while these inhibitory effects of salicin were abolished in the Gnat3-/- periodontitis mice." (PMID 38605968, 2024). "CXCL1, CXCL3, CXCL8, CSF3, IL1A, IL1B, and IL1RN all increased in JKs in periodontitis as predicted by our atlas/DEG analyses; alternatively, SKs were relatively less active compared to JKs." (PMID 38876998, 2024). "ICAM1+ fibroblasts expand in both human periodontitis and murine ligature-induced periodontitis model, which have upregulated expression of CCL2 and CXCL1 compared to other fibroblast populations." (PMID 39650645, 2024). "The machine learning algorithms here detected several recognized periodontitis biomarkers or inflammatory factors, including C3, C4A, CRCR4, and CXCL1, confirming the algorithms’ accuracy." (PMID 36457739, 2022). "The enrichment of TNFRSF21+ fibroblasts with high expression of CXCL1, CXCL2, CXCL5, CXCL6, CXCL13, and IL24 was detected in patients with periodontitis compared to healthy individuals." (PMID 35154475, 2022). "In patients with periodontitis, the supplementation of the diet with 3g of EPA and 2g of DHA markedly decreased the levels of CXCL1 and CXCL10 measured in the saliva as compared with controls." (PMID 35563819, 2022). "In addition to classical pro-inflammatory cytokines, our cytokine array analysis revealed significant upregulation of several chemokines in ligature-induced periodontitis, including thymus chemokine (CCL25), CINC-1 (CXCL1), and CINC-2α/β (CXCL3)." (PMID 41583507, 2026). "IL1A, IL1B, CXCL1, and CXCL3 displayed some correlation with highly infected cells —mostly suprabasal cells, likely explaining the differentiation effects predicted for these cells in periodontitis." (PMID 38876998, 2024). "In addition, it can act on endothelial cells via the CXCL1/ACKR1 and CXCL13/ACKR1 axes, and we hypothesized that this may promote endothelial cell angiogenesis, leading to gingival bleeding in periodontitis." (PMID 40370461, 2025). "PRKCQ-AS1, has not been studied in periodontitis, and our analysis showed that PRKCQ-AS1 may act as sponge of miR-141, miR-6512, miR-513c, and regulate the expression of CXCL1, PTGS2 (COX-2), THBS1 and PRKCQ." (PMID 36045361, 2022).
diabetes (23 papers, 2015 to 2025). "STZ-induced diabetes was associated with a significant decrease in the anti- inflammatory cytokine IL-10 and an increase in the proinflammatory cytokines CXCL-1, IFN-γ, IL-6, IL-18, and IL-33." (PMID 40649891, 2025). "One line of research is to analyze the association of CXCL1 with diabetes in obese individuals." (PMID 35806156, 2022). "Prior studies have associated CXCL1 and CXCL2 with neutrophil infiltration and myocardial injury in diabetes; our results expand on this by connecting CXCL1 expression to EndMT regulation, a link that remains relatively underexplored." (PMID 40426976, 2025). "Intriguingly, the hematopoietic depletion of NOD1 mitigated the diabetes-induced expression of CXCL1 and CXCL2; TNFα and IL10 remained unaffected." (PMID 38336763, 2024). "Bioinformatic analyses of transcriptomics data sourced from patients with diabetes corroborated the findings, revealing a significant upregulation of tubule cells-derived CXCL1 in tandem with infiltrating macrophages." (PMID 39608245, 2024). "There is also a link to diabetes as insulin signaling lowers LPS-induced CXCL1 expression in gingival fibroblasts, and short-chain fatty acid can lower cytokine-induced expression of CXCL1 and CXCL2 in HSC2 cells and gingival fibroblasts." (PMID 37762294, 2023). "Although a study on rats has not shown elevated brain concentrations of the rat equivalent of CXCL1 during diabetic ketoacidosis, the link between diabetes, neuroinflammation and CXCL1 needs to be investigated in a human model." (PMID 35806156, 2022). "KC‐GRO/CXCL1 is a cytokine that plays an important role in leukocyte recruitment, and mediates inflammation in diabetes." (PMID 31552707, 2019). "In this study, we have identified a group of APMB-specific analytes (IL-10, CXCL1, IL-12p40, IL-13, CCL22, CCL4, IL-17A, and TGFα) that correlates with several clinical phenotypes associated with more severe SAB (diabetes, dialysis dependence, metastatic infection, and cardiac vegetation)." (PMID 39966757, 2025). "Importantly, even after glucose control in diabetics, the macrophage is dysfunctional in these patients, exhibiting M1 pro-inflammatory phenotype and elevated levels of inflammatory chemokines CXCL1, CXCL5, and RANTES12." (PMID 35957939, 2022). "Finally, the whole heart extracts were examined with a Mouse cytokine array assay of 96 factors, which revealed a decrease in CD40, CTACK, CXCL1, MIP1γ, and sTNFRI, also supporting that glycyrrhizin halts myocardial inflammation in diabetes." (PMID 35281739, 2022). "However, l‐homoarginine supplementation did attenuate diabetes‐induced reductions in albuminuria, kidney histological changes, glomerular macrophage recruitment, KC‐GRO/CXCL1 levels, urinary TBARS excretion, and restored kidney nitrate + nitrite levels." (PMID 31552707, 2019). "Subsequently, we observed that the expression of CXCL1 and its receptor (CXCR2) was significantly increased in the kidneys of mice with HFD + STZ induced diabetes and DN patients." (PMID 34975537, 2021). "In line with previous findings, NOD macrophages produced higher protein levels of IL-6 and CXCL-1 (KC) and an upward tendency for TNFα and MCP-1, compared to non-diabetes-prone control C57BL/6 counterparts." (PMID 29095944, 2017). "Additionally, CXCL1, CCL22 and IL-17A significantly differed between APMB and ARMB when correlated with diabetes, dialysis, metastatic infection, or cardiac vegetation." (PMID 39966757, 2025). "Importantly, the expression of chemokines such as CXCL1 and CCL1 is modulated by NF-κB in many diseases such as cancer, diabetes, and neurological disorders." (PMID 39587693, 2024). "Taken together, these data strongly suggest that XMU-MP-1 may safeguard the kidney from diabetes-induced injury by preserving tubular MQC homeostasis, and subsequently suppress macrophage activation and renal inflammation by preventing CXCL1 production." (PMID 39608245, 2024).
diabetes (continued). "A case-control study found that GROa (CXCL1) is overexpressed in the brains of 23 Alzheimer’s disease patients, with no prior diagnosis of immunological diseases, hypertension, cardiac disease or diabetes, compared to age-matched controls." (PMID 35580794, 2022). "In conclusion, the results of our study suggest that increased spinal levels of CXCL1, CXCL5, CXCL9, or CXCL12 protein in mice after STZ treatment may participate in the development of diabetic neuropathic pain." (PMID 25789329, 2015).
lymph node metastasis (19 papers, 2017 to 2025). "High CXCL1 expression showed a significant association with lymph node metastasis and poor overall survival in patients with breast cancer." (PMID 36434686, 2022). "Univariate survival analysis demonstrated CXCL1 expression in CAFs, tumor size and lymph node metastasis were significantly associated with overall survival of ESCC patients treated with chemoradiotherapy." (PMID 28518141, 2017). "Authors observed that lymphatic endothelial cells (LECs) and LECs with lymph node metastasis exhibited significant differences in several genes including CXCL1." (PMID 38706513, 2024). "High CXCL1 expression in breast tumors is positively correlated with lymph node metastasis and TNM stage." (PMID 37108425, 2023). "A positive correlation was found between CXCL1 expression compared to the tumor staging, and lymph node metastasis in patients with non-small-cell lung cancer and was associated with poorer disease-free survival and overall survival." (PMID 36614235, 2023). "Some studies show that CXCL1 expression in colorectal tumors is positively correlated with lymph node metastasis, tumor size, and tumor stage." (PMID 37408240, 2023). "Comparative analysis of the CXC chemokine/receptor genes revealed significantly higher expression levels of genes encoding ELR+ CXC chemokines/receptors (CXCL1, CXCL3, CXCL6, CXCR1, and CXCR2) in bone metastases relative to lymph node metastases." (PMID 33195424, 2020). "CXCL1 expression was correlated with greater depth of invasion, whereas lymph node metastasis was correlated with increased CXCL1 and CXCL7 expression." (PMID 33182840, 2020). "The analysis results of 20 databases showed that mRNA CXCL1 positively associated with OS, PFS, TNM stage and lymph node metastasis for the ADC patients." (PMID 31998654, 2019). "Additionally, we discuss the clinical aspects by exploring how CXCL1 levels relate to cancer staging, lymph node metastasis, patient outcomes, chemoresistance, and radioresistance." (PMID 38673949, 2024). "This may explain the correlation of high CXCL1 expression in the tumor with the presence of lymph node metastasis in head and neck cancer." (PMID 37408240, 2023). "Serum CXCL1 levels are also positively correlated with lymph node metastasis." (PMID 37408240, 2023). "The CXCL1-positive group was significantly associated with negative lymph node metastasis (p = 0.043)." (PMID 35377900, 2022). "Similarly, mRNA expression of CXCL1 was elevated in ADC patients with lymph node metastasis (OR: 1.37, 95%CI: 0.99–1.90, P = 0.462, and I2 = 0.0%)." (PMID 31998654, 2019). "Likewise, serum CXCL1 levels are positively correlated with tumor stage and lymph node metastasis." (PMID 37408240, 2023). "CXCL1 was closely related to TNM stage, tumor size, and lymph node metastasis and predicted worse overall survival in adenocarcinoma." (PMID 31998654, 2019). "The analysis showed that the expression of CXCL1 in ADC was positively related to the TNM stage, tumor size and lymph node metastasis." (PMID 31998654, 2019). "The protein abundance of CXCL1 was positively correlated with tumor TNM stage (P = 0.0001), tumor size (P = 0.0032) and lymph node metastasis (P = 0.0234)." (PMID 31998654, 2019). "Also, a meta-analysis in various cancers showed that a higher CXCL1 expression was positively correlated with a more advanced TNM stage and a higher likelihood of lymph node metastasis with a poor OS." (PMID 38175424, 2024). "On the other hand, there is a study showing that stromal CXCL1 expression is not correlated with lymph node metastasis." (PMID 37108425, 2023). "CXCL1 expression in NSCLC tumors is positively correlated with the TNM stage and lymph node metastasis, but not with tumor size and carcinoembryonic antigen (CEA) levels." (PMID 38673949, 2024).
lymph node metastasis (continued). "Moreover, CXCL1 mRNA expression was upregulated in the LVSI+LN+ group compared to that in the LVSI+LN- group, suggesting that the high expression of chemokine CXCL1 may be involved in the recruitment of neutrophils to lymph vessels during the progression of lymph node metastasis in EEA." (PMID 33363026, 2020). "In addition, among all proteins tested, serum CXCL1 seems to be the best indicator in the differentiation between CRC patients with nodal involvement and patients without the presence of lymph node metastasis." (PMID 37509572, 2023).